APLP1 (amyloid beta precursor like protein 1)
Description:
May play a role in postsynaptic function. The C-terminal gamma-secretase processed fragment, ALID1, activates transcription activation through APBB1 (Fe65) binding (By similarity). Couples to JIP signal transduction through C-terminal binding. May interact with cellular G protein signaling pathways. Can regulate neurite outgrowth through binding to components of the extracellular matrix such as heparin and collagen I. The gamma-CTF peptide, C30, is a potent enhancer of neuronal apoptosis.
Synonyms: APLP
Tractability: Small molecule: a structure with a bound ligand is known; it has a high-quality binding pocket. Antibody: its Gene Ontology location is reachable by antibodies, with high confidence; UniProt places it where antibodies can reach, with medium confidence; UniProt predicts a signal peptide or a membrane-spanning region; the Human Protein Atlas places it where antibodies can reach.
Gene: Protein-coding gene on chromosome 19 (35,867,899 to 35,879,803, forward strand). Ensembl gene ENSG00000105290.
Subcellular location: Cell membrane; Cytoplasm (C30)
Subcellular location (Human Protein Atlas): Golgi apparatus; Plasma membrane; Nucleoplasm
Gene Ontology:
Molecular function: alpha-2A adrenergic receptor binding; alpha-2B adrenergic receptor binding; alpha-2C adrenergic receptor binding; identical protein binding; protein binding; heparin binding; transition metal ion binding
Biological process: cellular response to norepinephrine stimulus; negative regulation of adenylate cyclase-activating G protein-coupled receptor signaling pathway; animal organ morphogenesis; axonogenesis; central nervous system development; extracellular matrix organization; forebrain development; nervous system development; animal organ development
Cellular component: perinuclear region of cytoplasm; plasma membrane; basement membrane; Golgi apparatus; cytoplasm; membrane
Genetic constraint (gnomAD): Loss-of-function variants: 46 observed, 82.45 expected, observed/expected ratio (o/e) 0.56, 90% interval 0.44 to 0.71. The upper end of that interval is the gene's LOEUF score, 0.71, which puts it in group 2 of 6, group 1 being the genes least tolerant of losing a copy. Missense variants: 826 observed, 877.36 expected, observed/expected ratio (o/e) 0.94, 90% interval 0.89 to 1. Synonymous variants: 376 observed, 351.39 expected, observed/expected ratio (o/e) 1.07, 90% interval 0.98 to 1.16.
Homologues: Orthologues: chimpanzee APLP1 (99% identical), pig APLP1 (92% identical), guinea pig APLP1 (92% identical), rat Aplp1 (89% identical), mouse Aplp1 (89% identical), dog APLP1 (89% identical), macaque APLP1 (64% identical), zebrafish aplp1 (49% identical), tropical clawed frog aplp1 (44% identical), Drosophila melanogaster Appl (28% identical), Caenorhabditis elegans apl-1 (25% identical). Paralogues in human: APLP2 (41% identical), APP (37% identical).
Diseases named in the same sentence as APLP1 in open-access papers:
APLP1 is named in the same sentence as 47 diseases in open-access papers, as found by Europe PMC text mining. Sharing a sentence is not in itself a finding about the gene and the disease. The quoted sentences say what the papers report.
Alzheimer disease (13 papers, 2016 to 2024). A progressive, neurodegenerative disease characterized by loss of function and death of nerve cells in several areas of the brain leading to loss of cognitive function such as memory and language. "All differentially expressed proteins were downregulated in the cognitive dysfunction group with the exception of Amyloid-like protein-1 (APLP1), a synaptic protein suggested as a biomarker for Alzheimer’s disease, that was significantly increased." (PMID 36792657, 2023). "Taken together, the direct cleavage of APLP1 is a novel feature of the γ-secretase prompting a re-thinking of γ-secretase activity modulation as a therapeutic strategy for Alzheimer disease." (PMID 29382944, 2018). "While many studies have been focused on the pathologic role of APP in Alzheimer's disease, the physiological functions of APLP1 have remained largely elusive." (PMID 28537903, 2017). "The amyloid precursor protein (APP), a key player in Alzheimer’s disease (AD), is part of a larger gene family, including the APP like proteins APLP1 and APLP2." (PMID 37533067, 2023). "Aplp1 and Aplp2 are members of the amyloid precursor protein (APP), which is the source of the neurotoxic amyloid beta (Aβ) peptide involved in Alzheimer’s disease (AD)." (PMID 32759773, 2020). "Several studies have shown co-localization of APLP1 with APP in control subjects and Alzheimer’s disease brain plaques." (PMID 27186164, 2016). "APLP1, APLP2, and APP are well-established substrates of β-site amyloid precursor protein cleaving enzyme 1 (BACE1), playing crucial molecular roles in Alzheimer’s disease." (PMID 38370359, 2024). "Similar to APLP1, CLU has been described in the pathophysiogenesis of Alzheimer's disease." (PMID 35155457, 2021). "In addition, APLP1 is one of the substrates of BACE1, an enzyme involved in Alzheimer’s disease pathology." (PMID 27186164, 2016).
Parkinson disease (4 papers, 2009 to 2024). A progressive degenerative disorder of the central nervous system characterized by loss of dopamine producing neurons in the substantia nigra and the presence of Lewy bodies in the substantia nigra and locus coeruleus. "When targeting APP in the course of therapeutic intervention for AD, or APLP1 to inhibit α-synuclein propagation in Parkinson’s Disease, it will therefore be crucial to avoid compromising shared physiological functions within the APP family." (PMID 36385765, 2022). "Finally, a recent study also suggests that APLP1 has significance as a potential biomarker of Parkinson’ disease progression." (PMID 27186164, 2016). "These include genes in the pathways for amyotrophic lateral sclerosis (NEF3, NEFL, NEFH), Huntington's disease (CALM3, CLTC, CLTB), neurodegenerative disorders (APLP1, NEFH, FBXW7), Parkinson's disease (GPR37) and prion disease (APLP1, NFE2L2)." (PMID 19948073, 2009).
dementia (3 papers, 2022 to 2025). Loss of intellectual abilities interfering with an individual's social and occupational functions. "This network is related to the pathogenesis of dementia by APLP1 and MMEL1, which help amyloid metabolism and neurodegeneration." (PMID 41032496, 2025). "An example of a gene that exhibited DEUs was the amyloid-like protein 1 (Aplp1) gene, belongs to a family of proteins involved in neuronal development and in dementia." (PMID 36168804, 2022).
cognitive decline (2 papers, 2020 to 2023). "Since Aplp1 is particularly essential for synaptic maintenance, a decline in Aplp1 levels at younger age may be important for age-related cognitive decline." (PMID 37047250, 2023). "However, similar levels of Aplp1 in both lines of aged SAMP10 suggested that low level of Aplp1 at young age was more important for aging-related cognitive decline than Aβ accumulation." (PMID 32759773, 2020).
glioblastoma (2 papers, 2024 to 2025). The most malignant astrocytic tumor (WHO grade IV). "To further assess the diagnostic potential of APLP1+ EVs for brain diseases, we evaluated their expression in the blood of patients with glioblastoma multiforme (GBM) exhibiting EGFR and EGFRviii expression." (PMID 39742488, 2025).
neuroblastoma (2 papers, 2023 to 2024). Neuroblastoma (NB) is the most common solid, extracranial childhood tumor. "Taken together, we demonstrated in neuroblastoma cells that APLP1 shows the highest dimerization propensity of the APP family members, as well as the strongest presence at the cell surface." (PMID 37533067, 2023).
vascular dementia (2 papers, 2019 to 2025). A degenerative vascular disorder affecting the brain. "APLP1 expression levels are higher in vascular dementia (VaD) patients than in healthy controls." (PMID 30645580, 2019).
α-synucleinopathies (2 papers, 2024 to 2025). "Importantly, the impact of LAG3 and APLP1 on cerebral vasculature suggests that targeting this complex could have benefits beyond neuron-focused approaches, addressing the broader neurovascular implications of α-synucleinopathies." (PMID 39849529, 2025).
amyloidosis (1 paper, 2005). A disorder characterized by the localized or diffuse accumulation of amyloid protein in various anatomic sites. "An E693Q mutation in amyloid β (A4) precursor-like protein 1 (APLP1) leads to hereditary Dutch type – cerebral hemorrhage with amyloidosis ' '." (PMID 16321154, 2005).
Anxiety (1 paper, 2022). Intense feelings of nervousness, tension, or panic often arise in response to interpersonal stresses. "In addition, APLP1-KO mice spent more time along the wall of the open field arena at the expense of time spent in the center or intermediate zones, which may indicate reduced exploratory activity or increased anxiety." (PMID 36385765, 2022).
brain tumors (1 paper, 2025). "These APLP1+ BDEVs, when captured using immunocapture techniques, show promise as diagnostic tools for brain conditions, including both degenerative diseases and brain tumors (step I and step II)." (PMID 39742488, 2025).
clear cell renal cell carcinoma (1 paper, 2025). "Several studies have indicated that the overexpression of APLP1 is significantly linked to a lower OS rate in the early stages of clear cell renal cell carcinoma, thus suggesting its potential as a biomarker for the aggressiveness and prognosis of the disease." (PMID 41034734, 2025).
cognitive deficits (1 paper, 2025). "Age-matched littermates lacking APLP1 (APPflox/flox/APLP2flox/flox/APLP1−/−), which exhibit no functional or cognitive deficits and resemble WT mice, were used for control comparisons." (PMID 40512617, 2025).
coronary artery atherosclerosis (1 paper, 2020). "Studies in APP and APLP1/2 knockout (KO) mice suggest functional differences among the three family members and, significantly, a particular importance for APLP2 in the physiology of the cholesterol metabolism and coronary artery atherosclerosis." (PMID 32716039, 2020).
Down syndrome (1 paper, 2015). "A previous report showed an increase of APLP1β28 relative to the total amount of APLP1 peptides in CSF from AD subjects while we recently showed that the levels of APLP1β25, 1β27 and 1β28 in CSF from Down’s syndrome patients are decreased as compared to healthy controls." (PMID 26689589, 2015).
gastric cancer (1 paper, 2011). A primary or metastatic malignant neoplasm involving the stomach. "Of these 12 genes, 7 genes highly expressed in gastric cancer tissues were down-regulated (ITGB5, TYMS, MYB, APOC1, CBX5, PLA2G2A, KIF20A) and 5 low-expressed genes were up-regulated after vorinostat treatment (SCGB2A1, TCN1, CFD, APLP1, NQO1." (PMID 21931799, 2011).
lung carcinoma (1 paper, 2017). "Finally, higher APLP1 expression was observed in more advanced stages in lung cancer, implying a role of APLP1 in tumor metastasis." (PMID 28537903, 2017).
melanoma (1 paper, 2020). A malignant, usually aggressive tumor composed of atypical, neoplastic melanocytes. "Together with the conserved secretome profile, we found other proteins involved in protein aggregation, such as APP, APLP2, and APLP1, secreted by melanoma in a cell line‐specific manner." (PMID 32749065, 2020).
multiple sclerosis (1 paper, 2024). A progressive autoimmune disorder affecting the central nervous system resulting in demyelination. "Like APLP1, OLFM1 is an understudied player in multiple sclerosis, yet it demonstrates relevant and interesting neurobiology." (PMID 38880880, 2024).
periodontitis (1 paper, 2020). An acute or chronic inflammatory process that affects the tissues that surround and support the teeth. "Periodontitis induced by P. gingivalis-LPS increased the expression of APP and its homologs (APLP1 and APLP2)." (PMID 32714134, 2020).
primary progressive MS (1 paper, 2024). "Of particular significance was the discovery that low levels of APLP1 and CNDP1, or high levels of OLFM1, may distinguish relapsing remitting MS patients from primary progressive MS." (PMID 38880880, 2024).
Sensory neuropathy (1 paper, 2024). Peripheral neuropathy affecting the sensory nerves. "Other common hits included catalase/CAT which protects neurons from oxidative stress, AZGP1, a regulator of energy metabolism, amyloid precursor-like protein 1 (APLP1), the neurotrophic amyloid precursor protein (APP) and CCT4 which was linked to sensory neuropathy." (PMID 39115595, 2024).
Stroke (1 paper, 2019). Sudden impairment of blood flow to a part of the brain due to occlusion or rupture of an artery to the brain. "Of these, APLP1, NPTXR, ACTN1 also were detected in the brain tissue of CI/R-induced stroke mice." (PMID 30645580, 2019).
cancer (7 papers, 2017 to 2024). A tumor composed of atypical neoplastic, often pleomorphic cells that invade other tissues. "APLP1 is closely related to APP and APLP2, both of which are associated with aggressive cancers in other organs." (PMID 30603059, 2018).
neurodegenerative disease (4 papers, 2022 to 2025). A disorder of the central nervous system characterized by gradual and progressive loss of neural tissue and neurologic function. "Our findings compellingly argue for the diagnostic prowess of APLP1+ EVs in the domain of neurodegenerative disease diagnostics, primarily due to their neural origins." (PMID 39742488, 2025). "Other significantly downregulated genes were Resp18, Rtn1, Psap, Ubb, Aplp1, Cst3 and Itm2b, which are all associated with neurodegenerative diseases." (PMID 38017352, 2024). "A recent preprint suggests that SARS-CoV-2 induces amyloid aggregation of several proteins involved in neurodegenerative diseases such as APLP1, ApoE, clusterin, α2-macroglobulin, PGK-1, ceruloplasmin, nucleolin, 14–3-3, transthyretin, and vitronectin." (PMID 36362302, 2022). "Synthesizing our findings, APLP1+ EVs are postulated not merely as diagnostic markers but as seminal entities shaping the future trajectory of neurodegenerative disease diagnostics." (PMID 39742488, 2025). "The amyloid precursor protein family of proteins, including amyloid precursor-like proteins 1 and 2 (APLP1 and APLP2), has been the subject of intensive study due to its involvement in neurodegenerative diseases." (PMID 39596023, 2024).
tumor (4 papers, 2017 to 2023). "APLP1, involved in glucose homeostasis, was a novel finding showing strong association with OS in ccRCC but was over-expressed in normal compared to tumor samples (P < 0.001)." (PMID 30603059, 2018). "On the other hand, APLP1 was over-expressed in normal compared to tumor samples (P < 0.001)." (PMID 30603059, 2018). "Protein level of tumor promoting genes (GPRASP1, APLP1, ALPK3, SPTBN5, PCDHB14, LZTS3, RGL2) were higher in tumor tissues." (PMID 37237274, 2023). "We found that most genes with hazard ratio > 1 (GPRASP1, APLP1, ALPK3, SPTBN5, PCDHB14, LZTS3 and RGL2) have a higher expression in tumor tissues than normal tissues except LINGO1 and LZTS1." (PMID 37237274, 2023). "Four genes, G6PD, APLP1, GCNT3, and PLPP2, were also over-expressed in advanced stage (III and IV) and high grade (3 and 4) ccRCC and tumor with necrosis (PADJ<0.05)." (PMID 30603059, 2018). "However, although trending for significance, expression difference between tumor and normal samples for APLP1 was not statistically significant after adjusting for multiple comparison (PADJ = 0.06), while three other genes were over-expressed in tumor compared to normal tissue samples (PADJ < 0.05)." (PMID 30603059, 2018).
brain conditions (2 papers, 2016 to 2025). "Ongoing research endeavors are meticulously dissecting the sensitivity and specificity of APLP1+ EVs, juxtaposing the profiles of pathogenic proteins within these vesicles between patients harboring brain diseases and healthy counterparts." (PMID 39742488, 2025). "Harnessing APLP1 could revolutionize the diagnostic landscape, offering a window into the early stages of brain diseases." (PMID 39742488, 2025). "While our research robustly positions APLP1 as a brain-specific BDEV marker, given the significant enrichment of brain-associated proteins and miRNAs in APLP1+ EVs, the broader landscape of brain disease diagnosis via BDEVs remains intricate and demands further contemplation." (PMID 39742488, 2025). "Notably, APLP1 was prominent due to its pronounced expression in neurons and cells that commonly was affected in various types of brain diseases, positioning it as a leading candidate for a brain-specific EV marker." (PMID 39742488, 2025). "While APLP1 stands as a formidable contender in the realm of BDEV markers, its true potential might be realized in concert with a suite of other biomarkers, orchestrating a harmonized, multibiomarker system to pierce through the complexities of brain disease diagnosis." (PMID 39742488, 2025).
APLP1 also shares sentences with these, for which no sentence is quoted: infection (3 papers); amyotrophic lateral sclerosis (1); aneurysm (1); aortic stenosis (1); COVID-19 (1); esophageal cancer (1); Huntington disease (1); influenza (1); invasive ductal breast carcinoma (1); juvenile neuronal ceroid lipofuscinosis (1); kidney cancer (1); lung carcinoid tumor (1); Obesity (1); ovarian carcinoma (1); prion disease (1); prostate carcinoma (1); relapsing remitting MS (1); sarcoma (1); Sleep apnea (1); small intestinal tumor (1).